IL33 (interleukin 33)
Diseases named in the same sentence as IL33 in open-access papers (continued):
Sharing a sentence is not in itself a finding about the gene and the disease.
fetal growth restriction (2 papers, 2012 to 2024). A fetus that does not grow beyond the 10th percentile of conventionally accepted weight for gestational age. "The purpose of this study was to determine the association of IL-33, ST2, IL-1β, and T. gondii infection in women with intrauterine growth restriction." (PMID 39065188, 2024). "Therefore, a decrease in NO production is directly linked to lowered expression of the receptor for IL-33 (IL1RL1) and could reflect a supporting causative factor in the etiology of fetal growth restriction." (PMID 22808055, 2012).
fibrosarcoma (2 papers, 2016 to 2024). A malignant mesenchymal fibroblastic neoplasm affecting the soft tissue and bone. "Consistent with the mouse IL-33 fibrosarcoma model, Panc02 tumours also contained an exceptionally high number of TAMs as compared with other tumour types, validating the causational relation between IL-33 and TAM recruitment." (PMID 27150562, 2016). "In one case, the GPNMB growth effect depended on IL-33/ST2 signaling in MCA-1 fibrosarcoma cell cultures." (PMID 39052353, 2024).
Flavivirus Infections (2 papers, 2023). Infections with viruses of the genus FLAVIVIRUS, family FLAVIVIRIDAE. "We also assessed the role of IL-33/ST2 signaling in models of peripheral flavivirus infection, and observed increased mortality and weight loss in Il1rl1–/–mice." (PMID 37983247, 2023). "Our findings indicate that in the absence of IL-33 signaling, flavivirus infection leads to brain macrophage apoptosis, ingress of pathogenic peripheral monocyte-derived cells to the CNS, neuronal distress, astrocyte hyperactivity, and subsequent enhanced neuronal apoptosis and host demise." (PMID 37983247, 2023). "Our work also suggests that potentiating IL-33 signaling in the CNS could ameliorate pathology and sequelae associated with neurotropic flavivirus infection." (PMID 37983247, 2023). "Together, our studies reveal a source for CNS IL-33 during flavivirus infection and highlight its role in promoting microglial fitness in this setting." (PMID 37983247, 2023). "Collectively these data are consistent with a state of increased monocyte ingress and vascular leak, neuronal distress, and astrocyte hyperactivity in Il33–/–mice following flavivirus infection." (PMID 37983247, 2023). "We next sought to identify an effector cell population for the IL-33/ST2 axis during CNS flavivirus infection." (PMID 37983247, 2023). "We therefore wondered if the survival defect observed in Il33-/- or Il1rl1-/- mice upon neuroinvasive flavivirus infection was due to altered T cell recruitment or activation." (PMID 37983247, 2023). "Since our studies of knockout mice suggested a role for IL-33 in promoting survival to neuroinvasive flavivirus infection, we next sought to assess the CNS cell source of IL-33 in this setting." (PMID 37983247, 2023). "Together, these data suggest that IL-33/ST2 signaling is required during intracranial flavivirus infection to promote microglial viability and prevention of CNS pathology." (PMID 37983247, 2023). "Here, we identify the alarmin IL-33 and its receptor ST2 as critical for host survival to neuroinvasive flavivirus infection." (PMID 37090518, 2023). "We sought to assess the role of IL-33 and its receptor ST2 in controlling the CNS pathogenesis of flavivirus infection." (PMID 37983247, 2023). "In this study, we show that IL-33 signaling promotes survival during flavivirus infection, an effect apparently independent of a role for IL-33 in viral control." (PMID 37983247, 2023). "In the absence of intact IL-33/ST2 signaling in the brain, neuroinvasive flavivirus infection triggered aberrant recruitment of monocyte-derived peripheral immune cells, increased neuronal stress, and neuronal cell death, effects that compromised organismal survival." (PMID 37090518, 2023).
gastric disease (2 papers, 2015 to 2024). "IL-33, a member of the IL-1 family, is implicated in various inflammatory processes, and its roles in gastric diseases are an emerging area of research 32-33." (PMID 38617533, 2024). "IL33 gastropathy is associated with marked activation of Th2 lymphocytes and ILC2 and activation and expansion M2 macrophage recruitment, shown by fluorescence-activated cell sorter analysis and mRNA expression profiles." (PMID 28210674, 2015). "Here, we delineate the role of IL33 in the normal gastric mucosa and in response to gastropathy." (PMID 28210674, 2015). "This suggests that IL33-induced gastric pathology is dependent on infiltrating immune cells, which in turn induce STAT3, leading to gastropathy." (PMID 28210674, 2015). "Therefore, IL33 may inhibit H pylori–induced gastric disease by enhancing regulatory T-cell function, but not expansion." (PMID 28210674, 2015).
Giardia infection (2 papers, 2020 to 2021). "The effects of a Giardia-infection on the expression levels of IL-25 (IL-17E) and the alarmin IL-33 have, to our knowledge, never been studied." (PMID 32283818, 2020).
gingivitis (2 papers, 2023 to 2024). A disorder involving inflammation of the gums; may affect surrounding and supporting structures of the teeth. "Il33 expression had a peak in the GT during the gingivitis phase (day 1-3), followed by an increase in the PRT after IP, showing a trend consistent with the time course of bone resorption." (PMID 38548743, 2024).
Glucose intolerance (2 papers, 2016 to 2023). Glucose intolerance (GI) can be defined as dysglycemia that comprises both prediabetes and diabetes. "We used transgenic mouse models to selectively delete pericytic IL-33 expression and found that loss of this cytokine caused glucose intolerance due to impaired insulin secretion." (PMID 36967785, 2023). "Pericyte-selective deletion of the Il33 gene resulted in glucose intolerance due to impaired β-cell function." (PMID 36967785, 2023). "To define if pericytic IL-33 acts as a secreted cytokine, we tested whether exogenous IL-33 rescues glucose intolerance of ΔIl33Pericytes mice." (PMID 36967785, 2023).
Headache (2 papers, 2020 to 2025). Cephalgia, or pain sensed in various parts of the head, not confined to the area of distribution of any nerve. "Transforming Growth Factor α (TGFα) and Interleukin-33 were found to inversely correlate with headaches in the ME/CFS EV samples (r = −0.66, p = 0.002 and r = −0.63, p = 0.005 for TGFα and IL-33 respectively), and these correlations were unique in patients with ME/CFS compared to the control group." (PMID 33046133, 2020).
Hypoglycemia (2 papers, 2023 to 2025). A decreased concentration of glucose in the blood. "In agreement, the evaluation of biochemical markers at 21 dpi, a time point characterized by marked tissue damage, showed that IL-33 treatment ameliorated the hypoglycemia resulting from infection." (PMID 39883714, 2025). "This may suggest an unexplored potential role for IL-33 in hypoglycemia." (PMID 38053041, 2023).
immunodeficiencies (2 papers, 2022 to 2024). "Serum IL-33 levels were increased in ME/CFS patients without immunodeficiencies when compared to healthy control participants but also slightly increased when compared to ME/CFS patients with immunodeficiencies (Table A2)." (PMID 38202282, 2024). "Increased IL-33, which is a member of the IL-1 cytokine family, points towards a mucosal barrier leakage in ME/CFS patients without immunodeficiencies, as it acts as an alarmin to provide acute initial protection." (PMID 38202282, 2024).
intrahepatic cholangiocarcinoma (2 papers, 2023 to 2024). A carcinoma that arises from the intrahepatic bile duct epithelium in any site of the intrahepatic biliary tree. "In a desmoplastic intrahepatic cholangiocarcinoma (ICC) mouse model, cancer-associated fibroblasts (CAFs) recruited CD33+ MDSCs to the tumor and also mediated hyperactivation of 5LO metabolism in the MDSCs through CAF-derived IL-6 and IL-33." (PMID 38786066, 2024). "The results of the study showed that CAF increased the expression and activity of 5-lipoxygenase (5-LO) in MDSCs by secreting IL-6 and IL-33, which greatly contributed to the efficiency of tumor sphere formation and stemness marker gene expression in intrahepatic cholangiocarcinoma (ICC) cells." (PMID 37007004, 2023).
left ventricular hypertrophy (2 papers, 2022 to 2025). Enlargement of the LEFT VENTRICLE of the heart. "The interleukin 33 (IL-33) knockout mice showed increased left ventricular hypertrophy, ventricular dilatation, and fibrosis compared with wild-type mice." (PMID 35235759, 2022).
leishmaniasis (2 papers, 2020 to 2021). Infectious disease that is transmitted through the bite of hematophagous female phlebotomine sand flies. "This could explain the higher susceptibility of BALB/c mice driven by IL-33 during leishmaniasis." (PMID 32571430, 2020).
Listeria infection (2 papers, 2016). "Similarly, during Listeria monocytogenes infection, hepatocyte derived IL‐33 was found to increase macrophage proliferation in the liver 16, and assumed to be due to an amplification loop acting via basophil production of IL‐4." (PMID 27592711, 2016).
lung squamous cell carcinoma (2 papers, 2018 to 2024). "In contrast, association between higher IL-33 expression and survival was less consistent for squamous cell carcinoma of the lung among different datasets." (PMID 29499051, 2018).
lymphedema (2 papers, 2021 to 2025). Excess fluid collection in tissues, causing swelling. "Previous studies have reported that IL-33 expression is induced in the epidermis of lymphedema patients." (PMID 39941140, 2025). "This study clarified that the expression of IL-33 is induced in the nuclei of fibroblasts in dermal and subcutaneous tissues during lymphedema development but remains stable in epidermal cells." (PMID 39941140, 2025). "We investigated the induction of the IL-33/ST2 axis during lymphedema development using fluorescence immunohistochemistry and RT-qPCR." (PMID 39941140, 2025). "In human lymphedema patients, it has been reported that the expression of IL-33 increased in the superficial layer of the epidermis and plays an important role in the progression of lymphedema." (PMID 39941140, 2025). "In our current study, we clarified the fibroblast-derived IL-33 induction in the progression of lymphedema." (PMID 39941140, 2025). "These early inflammatory responses or direct mechanical stimuli from lymphedema exacerbation may induce the expression of IL-33 in the nuclei of cells in the dermal and subcutaneous tissues." (PMID 39941140, 2025). "In this study, the expression of Il1rl1 was induced after the increase in IL-33, suggesting that IL-33 is not only expressed in the nucleus but is also secreted from damaged fibroblasts into the lymphedema tissue, possibly leading to the increase in ST2+ cells." (PMID 39941140, 2025). "Therefore, we focused on the IL-33/ST2 axis as a candidate mechanism for lymphedema development." (PMID 39941140, 2025). "Membrane-bound ST2 is a functional component of IL-33 signaling, and an increase in Il1rl1 mRNA suggests that ST2+ cells infiltrate lymphedema tissues." (PMID 39941140, 2025). "These suggest that the IL-33/ST2 axis is involved in linking the innate and acquired immunity during the development of lymphedema." (PMID 39941140, 2025). "In response to IL-33, the expression of Il1rl1 mRNA increased from POD 7, indicating that ST2-expressing cells infiltrated the lymphedema tissues." (PMID 39941140, 2025). "Future studies should determine how the IL-33/ST2 axis affects Th2 cell infiltration and the pathological progression of lymphedema." (PMID 39941140, 2025). "Further experiments utilizing an inhibitor of the IL-33/ST2 axis and/or recombinant IL-33 will clarify the role of the IL-33/ST2 axis in lymphedema progression." (PMID 39941140, 2025). "A limitation of our research is that although the IL-33/ST2 axis is induced in the early stages of lymphedema, we have not yet identified which ST2+ cells are activated." (PMID 39941140, 2025). "IL-33 signaling via ST2 receptors (the IL-33/ST2 axis) has been proposed to be involved in a variety of Th2 cell-mediated diseases and may be involved in lymphedema." (PMID 39941140, 2025). "The activation of IL-33 and its receptor, the suppression of tumorigenicity 2 (ST2) signaling pathway, induces the differentiation of Th2 cells, but its involvement in lymphedema remains unclear." (PMID 39941140, 2025). "Interestingly, we found that patients with lymphedema have significantly increased expression of Th2-inducing cytokines (TSLP, IL33, IL25) in the epidermal cells of the lymphedematous limb, and that treatment with QBX258 decreased or normalized these changes." (PMID 34571811, 2021). "Therefore, epidermal IL-33 does not appear to contribute significantly to the development of lymphedema in this model." (PMID 39941140, 2025). "Therefore, since the increase in Il1rl1 indicates the induced infiltration of ST2+ cells, IL-33 may be involved in the infiltration of other ST2+ cells besides IL-13-expressing ILC2, leading to CD4+ T cell and Treg cell infiltration during lymphedema development." (PMID 39941140, 2025).
malignant salivary gland tumor (2 papers, 2018 to 2020). "In contrast to the study above, immunohistochemical analysis of nuclear IL-33 expression in patients with benign and malignant salivary gland tumors showed that IL-33 was most highly expressed in benign tumors." (PMID 30205617, 2018).
mastocytosis (2 papers, 2015 to 2025). A clonal myeloproliferative neoplasm characterized by the proliferation and accumulation of neoplastic mast cells in one or multiple organs or organ systems. "Additionally, Thymic Stromal Lymphopoietin (TSLP) acts together with IL-33 and also activates an abnormal mast cell for tryptase production in mastocytosis." (PMID 39859245, 2025). "Our finding that IL-25 is essential for vaccine-driven effector responses is somewhat surprising because it has been largely considered to be (alongside IL-33 and TSLP) a key inducer cytokine, acting at an early stage to drive ILC2s, mastocytosis and, in turn, Th2 immunity." (PMID 25816012, 2015).
Mcc (2 papers, 2022 to 2024). "The difference in the expression levels of IL-33 in V− and V+ MCC cell lines caused us to examine IL-33 levels in MCC tumors." (PMID 35409061, 2022). "All of the corresponding DEGs, except for Il-33, were up-regulated after Mcc HN-B infection." (PMID 39061526, 2024). "We speculated that the expression of Il-33 possibly varied at different stages of Mcc HN-B infection." (PMID 39061526, 2024). "The mean IL-33 plasma values were 26.14 ± 5.53 pg/mL and 37.81 ± 4.64 pg/mL for control and MCC patients, respectively." (PMID 35409061, 2022). "Western blot analysis confirmed higher IL-33 levels in V+ MCC cells than in V− MCC cells and HDF, although IL-33 expression levels did not vary between V− and V+ MCC patient samples." (PMID 35409061, 2022). "In this work, we focused on IL-33, one of the cytokines with higher transcript levels in the V+ MCC cell lines compared to V− MCC cell lines." (PMID 35409061, 2022). "In the current study, we examined the effect of MCPyV T-antigens (T-ags) on IL-33 expression and its functional role in MCC." (PMID 35409061, 2022). "Increased expression of IL-33, a potent modulator of tumor microenvironment, was observed in V+ MCC cell lines when compared to V− MCC-13 cells." (PMID 35409061, 2022). "To understand the enhanced level of IL-33 in V+ MCC cells compared with V− MCC cells, we investigated a possible involvement of MCPyV LT and sT in IL-33 expression regulation." (PMID 35409061, 2022). "We found that both viral proteins stimulated the promoter activity of the IL-33 receptors, ST2/IL1RL1 and IL1RAcP, and IL-33 protein expression was increased in MCC-13 cells transiently transfected with MCPyV T-ags." (PMID 35409061, 2022). "Of interest, significantly higher IL-33 and IL1RAcP protein levels were observed in MCC patient plasma compared to plasma from healthy controls." (PMID 35409061, 2022). "The MCPyV sT, LT, and tLT variants significantly upregulated IL-33 promoter activity, and increased IL-33 protein levels in MCC-13 cells at 24 h post-transfection." (PMID 35409061, 2022). "Significantly higher IL-33 and IL1RAcP levels were found in the MCC patients compared with the healthy individuals." (PMID 35409061, 2022). "The vast majority of the MCC samples analyzed expressed IL-33 (137/138) and IL1RAcP (134/138)." (PMID 35409061, 2022). "Because our results revealed a T-antigens-dependent induction of the IL-33/ST2 axis, IL-33/ST2 may play a role in the tumorigenesis of MCPyV-positive MCC." (PMID 35409061, 2022). "The induction of IL-33 expression was confirmed by transfecting MCC-13 cells with MCPyV LT." (PMID 35409061, 2022). "Several studies underscore a versatile role of the IL-33/T2-IL1RAcP pathway in the tumor microenvironment and tumorigenesis, thus making these proteins attractive therapeutic targets and potential biomarkers in MCC." (PMID 35409061, 2022). "The expression of IL-33, ST2, and IL1RAcP in MCC tissue samples, together with our in vitro data, suggest that the IL-33/ST2-IL1RAcP axis may play a role in MCC." (PMID 35409061, 2022). "Associations of IL-33, ST2/IL1RL1, IL1RAcP expression, clinicopathological factors (size, sex, age, stage [1 and 2 vs. 3 and 4], LT expression, presence of MCPyV DNA), and survival was investigated further with tissue microarray in a series of 138 MCC patient samples." (PMID 35409061, 2022). "Therefore, neutralizing the IL-33/ST2 axis may present a novel therapeutic approach for MCC patients." (PMID 35409061, 2022). "However, additional studies are required to establish that blocking the IL33/ST2 axis may have therapeutic potential for MCC treatment." (PMID 35409061, 2022). "We confirmed that IL-33/ST2 activated both pathways in MCC cells; this may explain the stimulatory effect on the MCPyV promoters, which contains putative binding sites for NF-κB and for ERK1/2 MAPK-regulated transcription factors, such as AP1, ATF/CREB, c-MYC, ELK1, and SP1." (PMID 35409061, 2022).
Mcc (continued). "This prompted us to compare IL-33, sST2/IL1RL1, and sIL1RAcP levels in the plasma of 12 healthy subjects and 12 MCC patients." (PMID 35409061, 2022). "All of the 23 MCC tissue samples displayed a uniform positivity for CK20 (dot-like cytoplasmic), IL-33 (cytoplasmic), ST2/IL1RL1 (nuclear), and IL1RAcP (nuclear and cytoplasmic)." (PMID 35409061, 2022). "The expression of IL-33 and its receptor ST2/IL1RL1 may constitute an autocrine or paracrine survival loop, which contributes to the growth and survival of MCC." (PMID 35409061, 2022). "The regulation of IL-33 expression in MCC is not understood." (PMID 35409061, 2022). "Immunohistochemical analysis demonstrated a significantly stronger IL-33, ST2, and IL1RAcP expression in MCC tissues compared to normal skin." (PMID 35409061, 2022).
mental disorder (2 papers, 2021). A disease that has its basis in the disruption of mental process. "IL-33 has also been implicated in other kinds of mental disorders." (PMID 34079543, 2021). "For this reason, the purpose of this point of view is to examine and to understand the possible link between mental disorders and interleukin 33 to clarify the role of this axis in the immune system." (PMID 33810498, 2021). "The purpose of this review is to examine and to understand the possible link between mental disorders and interleukin 33 to clarify the role of this axis in the immune system." (PMID 33810498, 2021). "According to literature, we found 13 research papers that evaluated interleukin 33 or interleukin 31 levels in subjects affected by mental disorders." (PMID 33810498, 2021). "We found 13 research papers that evaluated interleukin 33 or interleukin 31 levels in subjects affected by mental disorders." (PMID 33810498, 2021). "Moreover, recent studies, separately, showed that alarmins like IL-33, HMGB1, HSP, and S100 could play a key role in the pathogenesis of mental disorders." (PMID 33810498, 2021).